ABCC2 (ATP binding cassette subfamily C member 2)
Description:
ATP-dependent transporter of the ATP-binding cassette (ABC) family that hydrolyzes ATP to enable active transport of endogenous and xenobiotic substrates conjugated with glucuronate, glutathione or sulfate. Operates at apical membranes of polarized cells such as hepatocytes, renal and intestinal epithelial cells, where it mediates hepatobiliary and renal excretion of conjugated substrates preventing them from being recycled back into the bloodstream. Involved in canalicular bile production. Mediates hepatobiliary excretion of mono- and bis-glucuronidated bilirubin, enabling bilirubin detoxification. Mediates the efflux of steroid glucuronates and may regulate their hepatobiliary and renal metabolic clearance. Displays low affinity but high transport velocity toward androgen conjugates such as testosterone and dihydrotestosterone glucuronates as well as toward estrogen conjugates including estradiol, estrone and estriol glucuronates. May control the hepatobiliary and renal efflux of inflammatory leukotriene C4 (LTC4) and related cysteinyl leukotrienes. Transports sulfated bile salt such as taurolithocholate sulfate. It is functionally inactive toward androgen sulfates. Transports various anticancer drugs, such as anthracycline, vinca alkaloid and methotrexate and HIV-drugs such as protease inhibitors. Can confer resistance to several anticancer drugs including cisplatin, doxorubicin, epirubicin, methotrexate, etoposide and vincristine, by decreasing accumulation of these drugs in cells.
Synonyms: CMOAT; CMRP; MRP2; DJS; ABC30
Tractability: Small molecule: a structure with a bound ligand is known; a high-quality ligand is known; it belongs to a druggable protein family. Antibody: UniProt places it where antibodies can reach, with high confidence; its Gene Ontology location is reachable by antibodies, with high confidence; UniProt predicts a signal peptide or a membrane-spanning region. PROTAC: ubiquitination databases record sites on it; its protein half-life has been measured; a small molecule that binds it is known.
Target class: ABCC subfamily; ATP-binding cassette; Transporter; Primary active transporter
Safety:
Unwanted effects reported when the protein is acted on. In parentheses: how it was acted on, where the effect was seen, and who reports it.
adverse reactions (source: ClinPGx)
anemia (source: ClinPGx)
be resistant to treatment (source: ClinPGx)
cardiotoxicity (source: ClinPGx)
creatinine clearance (source: ClinPGx)
diarrhea (source: ClinPGx)
drug toxicity (source: ClinPGx)
hepatotoxicity (source: ClinPGx)
kidney tubular dysfunction (source: ClinPGx)
leukopenia (source: ClinPGx)
nausea (source: ClinPGx)
nausea and neutropenia (source: ClinPGx)
neurological adverse drug reactions (source: ClinPGx)
neurotoxicity syndromes (source: ClinPGx)
neutropenia (source: ClinPGx)
renal proximal tubulopathy (source: ClinPGx)
resistance to treatment (source: ClinPGx)
skin rash (source: ClinPGx)
thrombocytopenia (source: ClinPGx)
Gene: Protein-coding gene on chromosome 10 (99,782,640 to 99,852,594, forward strand). Ensembl gene ENSG00000023839.
Subcellular location: Apical cell membrane
Pathways (Reactome):
Drug ADME: Aspirin ADME; Atorvastatin ADME; Paracetamol ADME
Disease: Defective ABCC2 causes DJS
Metabolism: Heme degradation
Transport of small molecules: ABC-family protein mediated transport
Gene Ontology:
Molecular function: ABC-type glutathione S-conjugate transporter activity; ABC-type xenobiotic transporter activity; ATPase-coupled transmembrane transporter activity; bilirubin transmembrane transporter activity; protein binding; xenobiotic transmembrane transporter activity; ABC-type transporter activity; transmembrane transporter activity; ATP binding; ATP hydrolysis activity; toxin transmembrane transporter activity
Biological process: bile acid and bile salt transport; bilirubin transport; heme catabolic process; leukotriene transport; xenobiotic export from cell; xenobiotic transmembrane transport; negative regulation of gene expression; transepithelial transport; transmembrane transport; transport across blood-brain barrier; xenobiotic metabolic process; xenobiotic transport across blood-brain barrier; carboxylic acid transport
Cellular component: apical plasma membrane; cell surface; plasma membrane; intercellular canaliculus; membrane; vesicle
Genetic constraint (gnomAD): Loss-of-function variants: 157 observed, 181.88 expected, observed/expected ratio (o/e) 0.86, 90% interval 0.76 to 0.99. The upper end of that interval is the gene's LOEUF score, 0.99, which puts it in group 4 of 6, group 1 being the genes least tolerant of losing a copy. Missense variants: 1,804 observed, 1,928.6 expected, observed/expected ratio (o/e) 0.94, 90% interval 0.9 to 0.97. Synonymous variants: 648 observed, 727.54 expected, observed/expected ratio (o/e) 0.89, 90% interval 0.83 to 0.95.
Homologues: Orthologues: chimpanzee ABCC2 (99% identical), macaque ABCC2 (95% identical), dog ABCC2 (83% identical), rabbit ABCC2 (82% identical), pig ABCC2 (82% identical), guinea pig ABCC2 (79% identical), mouse Abcc2 (77% identical), rat Abcc2 (77% identical), Drosophila melanogaster MRP (45% identical), Caenorhabditis elegans mrp-7 (40% identical), Drosophila melanogaster Mrp5 (29% identical), Drosophila melanogaster Mrp4 (29% identical), and 9 more. Paralogues in human: ABCC1 (47% identical), ABCC3 (46% identical), ABCC6 (37% identical), ABCC5 (31% identical), ABCC4 (31% identical), ABCC10 (30% identical), ABCC9 (30% identical), ABCC8 (30% identical), ABCC12 (27% identical), ABCC11 (26% identical), CFTR (24% identical).
Diseases named in the same sentence as ABCC2 in open-access papers:
ABCC2 is named in the same sentence as 158 diseases in open-access papers, as found by Europe PMC text mining. Sharing a sentence is not in itself a finding about the gene and the disease. The quoted sentences say what the papers report.
Dubin-Johnson syndrome (36 papers, 2013 to 2025). Dubin-Johnson syndrome (DJS) is a benign, inherited liver disorder characterized clinically by chronic, predominantly conjugated, hyperbilirubinemia and histopathologically by black-brown pigment deposition in parenchymal liver cells. "Dubin–Johnson Syndrome is characterized by impaired excretion of conjugated bilirubin due to a mutation in the ABCC2/MRP2 gene." (PMID 41300483, 2025). "In Dubin-Johnson syndrome, the ABCC2 gene, which encodes ATP-binding cassette subfamily member C, is altered." (PMID 38651155, 2024). "Human ABC transporter ABCC2 transports conjugated bilirubin from hepatocyte to bile duct, dysfunction of which causes Dubin-Johnson syndrome." (PMID 38316776, 2024). "Meanwhile, mutations in the human ABCC2 gene result in Dubin-Johnson syndrome, an autosomal recessive disorder characterized by a defect in the transport of endogenous and exogenous anionic conjugates from hepatocytes into the bile." (PMID 37255458, 2023). "Mutations of the ABCC2 gene cause Dubin–Johnson syndrome, characterized by hyperbilirubinemia, elevated BAs’ levels, increased coproporphyrin isomer I in the urinary excretion, and deposition of melanin-like pigment in liver cells, but normal liver function." (PMID 36982896, 2023). "Based on the black-colored liver without nodularity, conjugated hyperbilirubinemia, the liver biopsy results of the coarse pigment in centrilobular hepatocytes, and the ABCC2 mutation, Dubin-Johnson syndrome was diagnosed." (PMID 36555809, 2022). "ABCC2 is known to trigger Dubin–Johnson syndrome, which causes an increase in conjugated bilirubin levels." (PMID 32477112, 2020). "Pathogenic variants in ABCC2 can cause Dubin-Johnson syndrome, a benign autosomal recessive disorder characterized by hyperbilirubinemia with no clinical feature shared with our patients." (PMID 32038177, 2020). "Dubin-Johnson syndrome (DJS) is characterized by conjugated hyperbilirubinemia induced by a mutation of the adenosine triphosphate-binding cassette subfamily C member 2 (ABCC2) gene." (PMID 32758197, 2020). "Mutations in these genes are associated with diseases, including cystic fibrosis (ABCC7/CFTR), Tangier disease (ABCA1/CERP), Dubin–Johnson syndrome [ABCC2/multidrug resistance‐associated protein (MRP2)] and gout [ABCG2/breast cancer resistance protein (BCRP)]." (PMID 33128234, 2020). "Genetic studies confirmed missense homozygous variant p.Trp709Arg in the ATP-binding cassette sub-family C member 2 gene ABCC2 that encodes the Multidrug resistance-associated protein 2 that causes Dubin–Johnson syndrome." (PMID 28923092, 2017). "Dubin-Johnson syndrome is caused by several different mutations in ABCC2, and is associated with a failure to excrete conjugated bilirubin glucuronides in the bile, resulting in elevated levels of conjugated bilirubin in the blood." (PMID 25793771, 2015). "Mutations in ABCC2 (ENSG00000023839) cause Dubin–Johnson syndrome (MIM # 237500), a well-characterized autosomal recessive disorder that leads to episodic jaundice and conjugated hyperbilirubinemia in times of metabolic stress." (PMID 23836506, 2013). "Five variants in UGT1A1 gene causing Crigler-Najjar syndrome, type I/II were detected in four unrelated patients (3 homozygous and 1 compound-heterozygous), while two unrelated patients were reported with two disease causing variants in the ABCC2 gene causing Dubin-Johnson syndrome." (PMID 41165782, 2025). "Several genetic variants may affect its activity, with some associated with Dubin–Johnson syndrome or the susceptibility to develop diclofenac-induced hepatotoxicity, such as the ABCC2 rs717620 polymorphism." (PMID 36982896, 2023). "For example, patients with genetic hyperbilirubinemias such as Dubin-Johnson syndrome, a disorder involving mutations in the bilirubin transporter ABCC2, or Crigler-Najjar Type 1, a disorder involving mutations in the bilirubin glucuronosyltransferase UGT1A1, rarely complain of pruritus." (PMID 30657454, 2019).
Dubin-Johnson syndrome (continued). "The presence of particular polymorphisms of MRP2/ABCC2 may cause Dubin-Johnson syndrome." (PMID 30018187, 2018). "Dubin-Johnson Syndrome (DJS) is a condition characterized by conjugated hyperbilirubinemia resulting from ABCC2 deficiency in humans." (PMID 25268163, 2014). "Well-known examples are the Dubin–Johnson syndromes, where patients have elevated conjugated bilirubinemia caused by mutations affecting MRP2 (ABCC2)." (PMID 39713147, 2024). "Bilirubin is conjugated in hepatocytes and excreted to bile duct via the ATP-binding cassette transporter ABCC2, dysfunction of which would lead to Dubin-Johnson syndrome." (PMID 38316776, 2024). "Recent studies demonstrated that patients with Dubin-Johnson syndrome and Abcc2 knockout rats expressed the Abcc3 gene at a higher level in comparison to WT rats." (PMID 30611276, 2019). "Twenty-two of the 48 human ABC transporters have been implicated in causing monogenetic diseases, such as Tangier disease (gene: ABCA1) and Dubin-Johnson syndrome (gene: ABCC2)." (PMID 30611276, 2019). "This has been confirmed through diseases such as intrahepatic cholestasis and Dubin-Johnson syndrome caused by mutations in ABCB4 and ABCC2, respectively." (PMID 24732756, 2014). "In addition, 20 patients were diagnosed with a genetic hyperbilirubinemia syndrome: Dubin-Johnson syndrome (ABCC2, n = 17), Rotor syndrome (SLCO1B1/B3, n = 1), Crigler-Najjar syndrome (UGT1A1, n = 1) and Gilbert syndrome (UGTA1, n = 1)." (PMID 35626323, 2022). "Genetic diseases have shed light on the membrane transporters for BR and its conjugates The Dubin-Johnson syndrome is caused by mutations in the protein MRP2, encoded by ABCC2, which drastically reduce the capacity of the liver to excrete the conjugated pigment into the bile." (PMID 29259555, 2017). "Dual-hereditary jaundice (Dubin–Johnson syndrome (DJS) and Gilbert’s syndrome (GS)) is a rare clinical entity resulting from defects of the ATP binding cassette subfamily C member 2 (ABCC2) and UDP glucuronosyltransferase family 1 member A1 (UGT1A1) genes with autosomal recessive inheritance." (PMID 36274106, 2023).
breast carcinoma (23 papers, 2010 to 2025). "Regarding mutation frequency, the highest mutation rates in breast cancer tissues were observed in ABCC2 and ABCC9." (PMID 40641097, 2025). "Our findings showed that the ABCC2 SNP rs2273697 was significantly associated with age at breast cancer diagnosis." (PMID 31391850, 2019). "None of the ABCC1 SNPs showed any significant association with the clinical characteristics of BC, but the ABCC2 SNPs rs2273697 and rs717620 were found to be significantly associated with age at breast cancer diagnosis (p value = 0.042) and breastfeeding status (p value = 0.05), respectively." (PMID 31391850, 2019). "For example, CYP19 genotypes might modulate AI metabolism; the alleles of ABCC2 have been shown to have an additive effect on recurrence-free survival outcome of adjuvant tamoxifen therapy for breast cancer patients." (PMID 21187922, 2010). "ABCC2 is expressed at a high level in tamoxifen-resistant breast cancer, and ABCC2 upregulation suggests a poor prognosis in pancreatic cancer." (PMID 33953166, 2021). "In the present study, single nucleotide polymorphisms (SNPs) from the ABCC1, ABCC2, ABCB1, and ABCG2 genes were screened in breast cancer patients and healthy volunteers from the Jordanian-Arab population." (PMID 31391850, 2019). "Overall anemia (grade 1–2) high risk genetic factors belonged to all three functional groups – DNA repair (ERCC1, p.Asn118=), metabolism (GSTT1 and GSTM1 present) and transport (ABCC2, p.Val417Ile), with addition of breast cancer triple negativity." (PMID 29507678, 2018). "Studies have reported that ABCB5, ABCB8, ABCB10, ABCC2–5, and ABCC10 are overexpressed in breast cancer cells or are associated with breast cancer progression." (PMID 30202239, 2018). "Risk of FAC-related anemia of any grade was elevated by polymorphic allele C of p.Asn118= (rs11615) variant in ERCC1 gene, common homozygote GG of ABCC2 p.Val417Ile (rs2273697) polymorphism, presence of both GSTT1 and GSTM1 genes and triple-negativity of breast cancer." (PMID 29507678, 2018). "We have shown that loss of WISP2 expression in breast cancer cells leads to acquisition of the CD44+/CD24− phenotype, ALDH+ expression, upregulation of the ABCC2 drug efflux pump expression known to be associated with less differentiated cells and stem cells, although they lack SP cells." (PMID 24498388, 2014). "With regard to the clinical characteristics of BC, the ABCC2 SNPs rs2273697 and rs717620 were found to be significantly associated with age at breast cancer diagnosis and breastfeeding status, while the ABCB1 SNP rs1045642 was significantly associated with age at breast cancer diagnosis." (PMID 31391850, 2019). "Deep deletions were significantly more prevalent in prostate cancer than in breast cancer, with frequent occurrences in ABCG2, ABCG1, ABCC4, ABCA2, ABCC2, ABCC7/CFTR, and ABCC9." (PMID 40641097, 2025). "Deep deletions were significantly more prevalent in prostate cancer tissues compared to breast cancer tissues, where they were relatively rare and limited to ABCG2, ABCC4, ABCA2, ABCC2, and ABCC9." (PMID 40641097, 2025). "In contrast, breast cancer exhibited relatively lower deep deletion rates, restricted to ABCG2, ABCC4, ABCA2, ABCC2, and ABCC9." (PMID 40641097, 2025). "For metformin, the highest number of its targets were associated with malignant neoplasm of the prostate (six genes) and breast carcinoma (seven genes: ABCB11; ABCC2; ABCC3; ABCC4; DHFR; DPP4; SLC22A1)." (PMID 36046822, 2022). "On the other hand, low expression of TTF2, ABCC2, FLOT2, and NLRP2 was correlated with poor prognosis in HER2-positive breast cancer patients, whereas their low expression was correlated with better prognosis in the overall METABRIC cohort." (PMID 32640677, 2020). "ABCB1, ABCB5, ABCB8, ABCC1, ABCC2, ABCC3, and ABCG2 were considered to confer resistance to doxorubicin on the breast cancer cells." (PMID 30202239, 2018).
breast carcinoma (continued). "Similarly, paclitaxel and docetaxel are also responsible for an increased expression of ABCC2 and ABCB1 genes in breast cancer." (PMID 38534323, 2024). "Expression of ABCB1, ABCC2, ABCG2, SLC22A16, and SLCO1A2 was significantly higher in normal breast tissue compared to tumorous tissue, while SLC22A1 and the tumor marker ESR1 showed a significantly higher expression in breast cancer tissue." (PMID 35008681, 2021). "Our results of cumulative analyses further emphasize the importance of changes that occur simultaneously in cellular transport (p.Ser893Ala/Thr in ABCB1, c.-24C>T in ABCC2) and DNA repair systems (p.Lys751Gln in ERCC2) for the outcome of treatment in breast cancer patients." (PMID 27527855, 2016). "In the present study, four SNPs of ABC transporter genes, namely ABCC1, ABCC2, ABCB1, and ABCG2, were screened in Jordanian Arabs with and without breast cancer." (PMID 31391850, 2019).